RETN (resistin)
Diseases named in the same sentence as RETN in open-access papers (continued):
Sharing a sentence is not in itself a finding about the gene and the disease.
chronic hepatitis B (4 papers, 2017 to 2024). "This study investigated the association between serum resistin and fibrosis severity and the possible marker role of resistin in the inflammatory process of chronic hepatitis B." (PMID 28061755, 2017). "Proinflammatory effects of resistin and anti-inflammatory effects of adiponectin have been shown in various metabolic and inflammatory diseases (atherosclerosis, diabetes mellitus, fatty liver disease, viral hepatitis), including patients with chronic hepatitis B." (PMID 35510200, 2022). "However, the mechanism of resistin in the inflammatory process of chronic hepatitis B is unclear, further studies are needed to elucidate how resistin works in the progress of liver injury, and the cross-talk between resistin and IL-17 or TGF-β signaling pathways." (PMID 28061755, 2017). "In a study of patients with chronic hepatitis B infection, resistin correlated with SGPT but not with SGOT." (PMID 39519480, 2024). "When comparing HCC and non-HCC cases, profiles of HCC and non-HCC chronic hepatitis B patients were rather different with resistin being the most predictive cytokine followed by IL-7 and IL-8 (AUC = 0.744) and less so for chronic hepatitis C patients (AUC = 0.635)." (PMID 28928388, 2017). "Furthermore, cytokine profiles in chronic hepatitis B non-HCC patients differed from those of patients with non-viral disease with AUROC = 0.840 with leptin, resistin, IL-8, M-CSF, TNF-β, and sFas ligand as the top 6 cytokines with distinguishing levels." (PMID 28928388, 2017).
coronary artery calcification (4 papers, 2017 to 2023). Calcification of the coronary artery, used as a measure of coronary atherosclerosis, a risk factor for myocardial infarction. "Resistin was positively correlated with the degree of thoracic aortic calcification and coronary artery calcification, all suggesting a significant association between resistin and the severity of CVD." (PMID 37645520, 2023).
cystic fibrosis (4 papers, 2018 to 2023). Autosomal recessive disorder caused by pathogenic variants in the CFTR gene (cystic fibrosis transmembrane conductance regulator), which encodes a chloride and bicarbonate channel expressed in epithelial cells, and follow the diagnosis criteria. "In a recent study, plasma and sputum resistin levels were elevated in patients with cystic fibrosis-related lung disease and were associated with impaired lung function." (PMID 35592858, 2022). "Furthermore, increases in resistin levels were associated with other diseases such as cystic fibrosis, vascular diseases, and metabolic disorders." (PMID 29584687, 2018). "Under pathophysiological conditions, resistin has been observed in the lungs of patients with cystic fibrosis, scleroderma (SSc), and idiopathic pulmonary fibrosis." (PMID 35592858, 2022).
diabetic nephropathy (4 papers, 2018 to 2025). "Logistic regression demonstrated that plasma resistin was associated with a higher risk of diabetic nephropathy (odds ratios (OR) = 2.255, P = 0.001)." (PMID 34996484, 2022). "Additionally, many studies have linked high resistin levels with diabetic nephropathy while few studies have linked them to novel subgroups of T2DM patients." (PMID 34996484, 2022). "It turns out that resistin was positively correlated with indicators related to the amount of iron in the body in patients with diabetic kidney disease." (PMID 39796247, 2025). "It is possible that in the SIRD group, resistin participates in a more important mechanism to promote diabetic nephropathy attributable to its proinflammatory potential." (PMID 34996484, 2022). "At the same time, resistin was shown to be related to diabetic nephropathy in the logistic regression analysis in the results." (PMID 34996484, 2022). "Therefore, resistin may be more closely associated with diabetic nephropathy than HOMA2-IR." (PMID 34996484, 2022). "In a prospective cohort study of 150 patients with diabetic nephropathy, increased resistin and visfatin levels at baseline were found to be independent predictors of cardiovascular mortality." (PMID 29848323, 2018). "The SIRD group had high levels of resistin, and resistin may serve as a promising predictor for diabetic nephropathy in this group." (PMID 34996484, 2022). "Although previous publications have explored the relationship between resistin and diabetic nephropathy after stratifying patients by BMI or non-alcoholic fatty liver, the present study provides more precise results based on five variables rather than merely one indicator." (PMID 34996484, 2022). "The findings indicated that resistin might be an effective predictor for diabetic nephropathy in the SIRD group." (PMID 34996484, 2022). "Logistic Regression Analysis of ANGPTL8 and resistin for diabetic nephropathy in all patients." (PMID 34603198, 2021). "Whether or not the alteration in ANGPTL-8 and resistin level can be a predictive maker for increased diabetic nephropathy risk remains unclear." (PMID 34603198, 2021). "ROC plots were generated to assess the predictive value of resistin and HOMA2-IR for diabetic nephropathy." (PMID 34996484, 2022). "According to receiver operating characteristic (ROC) curves, the area under the curve (AUC) of resistin (0.748, 95% CI 0.610–0.887) was significantly greater than that of HOMA2-IR (0.447, 95% CI 0.280–0.614) (P < 0.05) for diabetic nephropathy in the SIRD group." (PMID 34996484, 2022). "Logistic regression analysis of ANGPTL8 and resistin respectively for diabetic nephropathy in the non-NAFLD and NAFLD population." (PMID 34603198, 2021).
endotoxemia (4 papers, 2004 to 2019). "In human study participants, experimental endotoxemia, which produces an insulin-resistant state, causes a dramatic rise in circulating resistin levels." (PMID 15578112, 2004). "A previous study reported a dose-dependent increase in resistin gene and protein expression by the human macrophages and by healthy human subjects with induced endotoxemia following LPS administration." (PMID 29138754, 2017). "Remarkably, resistin levels rose dramatically because of endotoxemia, peaking 8–16 h after LPS administration." (PMID 15578112, 2004). "The increase in resistin protein levels correlated with increased resistin gene expression in peripheral blood mononuclear cells following systemic endotoxemia." (PMID 15578112, 2004). "Experimental endotoxemia in healthy volunteers, based on the well-established gram-negative bacterial inflammatory response in humans, induces a dramatic elevation of circulating resistin levels." (PMID 15578112, 2004).
fibrosis (4 papers, 2020 to 2025). the formation of excess fibrous connective tissue in an organ or tissue in a reparative or reactive process. "Adipocytes are active cells filled with adipokines, including adiponectin, resistin, and visfatin, which are lost in SSc fibrosis." (PMID 36389675, 2022). "Beyond the vasculature, resistin exerts direct detrimental effects on the myocardium by disrupting cardiomyocyte calcium handling and mitochondrial energetics, inducing pathological hypertrophy, and stimulating robust cardiac fibrosis via mechanisms involving JAK/STAT3 and TGF-β signaling." (PMID 41347124, 2025).
hypoadiponectinemia (4 papers, 2011 to 2023). "In obese children and adolescents, hypoadiponectinemia and hyperleptinemia, as well as higher values of resistin were well correlated with an atherogenic lipid profile and markers of IR." (PMID 32344627, 2020).
ischemia (4 papers, 2010 to 2025). A hypoperfusion of the BLOOD through an organ or tissue caused by a PATHOLOGIC CONSTRICTION or obstruction of its BLOOD VESSELS, or an absence of BLOOD CIRCULATION. "The cardioprotective effect of resistin was observed in an experiment using a mouse heart perfusion model, where pretreatment with resistin limited damage during ischemia by reducing cardiomyocyte apoptosis and the infarct size." (PMID 40283140, 2025). "After brain I/R, the exogenous administration of resistin exerted anti-apoptotic, protective activity by decreasing the expression of Bax protein, demonstrating the ability for resistin to cross the impaired BBB after ischemia injury." (PMID 35806921, 2022).
liver inflammation (4 papers, 2008 to 2024). "Proteins that uniquely distinguish HCC patients with low AFP from patients with hepatitis include IL1RN, IFNG, CDKN1A, RETN, CXCL14, and FGF2." (PMID 19578489, 2008). "Importantly, we also identified 8 proteins that significantly differentiate HCC patients with ‘normal’ levels of AFP (< 20 ng/ml) from hepatitis patients (p < 0.05) (IL1RN, IFNG, CDKN1A, RETN, CXCL14, CTNNB, FGF2, and SELL)." (PMID 19578489, 2008).
lupus nephritis (4 papers, 2008 to 2022). Glomerulonephritis in the context of systemic lupus erythematosus. "In another study, the serum and urine resistin levels of patients with lupus nephritis (LN) were elevated, which correlated with the relevant indicators of LN renal insufficiency and could be used as a potential marker of LN nephropathy." (PMID 35592858, 2022). "Whether this is due to high systemic inflammation in the patients having ongoing lupus nephritis or to resistin merely being accumulated in the serum of patients with low GFR cannot be decided." (PMID 18234104, 2008).
melanoma (4 papers, 2018 to 2023). A malignant, usually aggressive tumor composed of atypical, neoplastic melanocytes. "In the present study, we observed that leptin and resistin cause impairment in the effect of DTIC on melanoma cells in vitro." (PMID 29568521, 2018). "Upon leptin and resistin treatment using A375 melanoma cell line, fatty acid synthase (FASN) and caveolin 1 (Cav-1), respectively, were found increased." (PMID 32509589, 2020). "In a recent mouse model using ob/ob and db/db strains the roles of leptin and resistin in the dacarbazine (DTIC) therapy in melanoma was reported." (PMID 32509589, 2020). "Our results clearly indicated that leptin and resistin partly contribute to melanoma progression and in impairing the outcome of dacarbazine therapy." (PMID 29568521, 2018). "Collectively, these data suggest that both leptin and resistin partly play a crucial role in melanoma growth and adversely affect the chemotherapeutic outcome by modulating the molecules which are involved in tumor growth and drug resistance." (PMID 29568521, 2018). "Both leptin and resistin not only enhance proliferation of melanoma cells but also are involved in impairing the therapeutic efficacy of DTIC." (PMID 29568521, 2018). "ob/ob and db/db mouse models were used in this study to evaluate the role of leptin and resistin towards the outcome of dacarbazine (DTIC) therapy in melanoma." (PMID 29568521, 2018). "The present study is aimed at unraveling the specific role of leptin and resistin in melanoma growth and the chemotherapeutic outcome using appropriate in vitro and in vivo approaches." (PMID 29568521, 2018). "Further, it was observed that leptin and resistin impaired the response of melanoma cells to DTIC via upregulation of heat shock protein 90 (Hsp90) and P-glycoprotein (P-gp) respectively." (PMID 29568521, 2018). "In a nutshell, this study highlights the role of leptin and resistin in melanoma growth, and impairment in the chemotherapeutic outcome." (PMID 29568521, 2018). "In the present study, we investigated the specific role of leptin and resistin in melanoma cell growth, proliferation, and the outcome of DTIC-based chemotherapy." (PMID 29568521, 2018). "Leptin and resistin enhance proliferation of melanoma cell lines and hinder DTIC efficacy." (PMID 32509589, 2020). "Firstly, to explore whether leptin and resistin could have any role in modulating the sensitivity of melanoma cells to DTIC, A375 cells were treated with DTIC in the presence or absence of leptin or resistin." (PMID 29568521, 2018). "To get insights into the role of leptin and resistin in causing attenuation in the response to DTIC, we intended to analyze the status of FASN and Cav-1 which are upregulated in melanoma in the obese (HFD) mice, and are known to be involved in resistance to cancer chemotherapy." (PMID 29568521, 2018). "However, cycloheximide chase experiment confirms that leptin and resistin cause the stabilization of FASN and Cav-1 protein levels respectively in melanoma cells." (PMID 29568521, 2018). "Nonetheless, our in vitro studies (especially treatment of melanoma cells with leptin and resistin, as well as their immune-depletion) demonstrate that these adipokines critically affect melanoma growth, and the chemotherapeutic outcome, by modulating melanoma promoting proteins." (PMID 29568521, 2018). "We examined whether adipocytes cocultured with melanoma cells demonstrate decreased expression of adipocyte differentiation markers such as leptin, resistin, adiponectin, and fatty acid binding protein (FABP4) by assessing the expression of these genes in the cells." (PMID 37481560, 2023). "Therefore, resistin-mediated impairment of DTIC treatment in melanoma cells could be due to collective involvement of Cav-1 and P-gp, both being integral component of plasma membrane of cancer cells." (PMID 29568521, 2018).
melanoma (continued). "Here, we have shown the role of important adipokines leptin and resistin in growth and the outcome of DTIC therapy in melanoma." (PMID 29568521, 2018). "Moreover, our data show that depletion of leptin and resistin from the serum collected from obese mice resulted in the improved response of melanoma cells as compared to the undepleted serum suggestive of their role in modulating the response of melanoma cells to DTIC." (PMID 29568521, 2018). "Leptin and resistin are both secreted by adipocytes and affect synthesis of FASN (fatty acid synthase) and the activation of the AKT-based signal transduction pathway, thus promoting the proliferation of melanoma cells." (PMID 37481560, 2023). "We noticed that mature adipocytes express a high level of selected adipokines (leptin, adiponectin, resistin), lipid transport protein (FABP4), and enzymes related to lipid synthesis (FADS, SC4MOL, FASN), while their levels decrease in adipocytes cocultured with melanoma cells." (PMID 37481560, 2023). "Although, our in vitro results established the fact that both leptin and resistin are involved in impairing the response of melanoma cells to DTIC, it is difficult to validate their role in vivo due to lack of resistin knockout animals as well as resistin neutralizing antibody." (PMID 29568521, 2018).
Myocardial fibrosis (4 papers, 2023 to 2025). "In experimental models, resistin promotes myocardial fibrosis via TGF-β/Smad pathways, stimulating collagen synthesis in cardiac fibroblasts and increasing extracellular matrix deposition." (PMID 41347124, 2025). "Cardiac overexpression of resistin using AAV-9 technology worsened cardiac dysfunction and myocardial fibrosis." (PMID 37035745, 2023).
polyp (4 papers, 2010 to 2024). A usually exophytic mass attached to the underlying tissue by a broad base or a thin stalk. "However, significantly higher resistin concentrations were observed in patients diagnosed with colon polyps and prediabetes than in healthy individuals (polyp-free with normal glucose tolerance)." (PMID 39184804, 2024). "Moreover, in the studied sample, CXCL10 levels increased and resistin levels decreased in CRC compared to the control and polyp groups, respectively." (PMID 38003638, 2023). "Moreover, resistin concentrations are not significantly related to body mass index (BMI) values, polyp localization, or vascular invasion." (PMID 39184804, 2024).
renal cell carcinoma (4 papers, 2018 to 2025). "Background and Objectives: To investigate the clinical significance of adipokines’ [leptin, leptin receptor (leptin-R), adiponectin, and resistin] expression on the characteristics and survival outcomes of patients with renal cell carcinoma (RCC)." (PMID 41010935, 2025). "For instance, resistin was recently reported as a predictive factor for the recurrence and long-term prognosis in renal cell cancer." (PMID 30517161, 2018).
schizophrenia (4 papers, 2012 to 2025). A major psychotic disorder characterized by abnormalities in the perception or expression of reality. "Additionally, prostaglandin-H2, nerve growth factor, and resistin, identified in the schizophrenia MR study, were also associated with SLE and RA." (PMID 40082977, 2025). "While its connection to language is not clear, it has been associated with traits such as drinking behavior and circulating levels of resistin, a hormone involved in inflammation, and some protein-truncating variants have been reported for this gene in the context of schizophrenia." (PMID 34773992, 2021). "One study found high plasma resistin levels in both first-episode schizophrenia patients and chronic schizophrenia patients, suggesting a role for resistin in the inflammatory process in both acute and chronic phases of psychosis." (PMID 37479996, 2023). "This showed that 9 of the analytes (C-reactive protein, cortisol, resistin, TIMP-1, chromogranin A, VEGF, thrombopoetin, alpha-2 macroglobulin, and glutathione S-transferase) were also found to be reproducibly altered between schizophrenia and control subjects in serum." (PMID 23118852, 2012).
Shock (4 papers, 2017 to 2023). The state in which profound and widespread reduction of effective tissue perfusion leads first to reversible, and then if prolonged, to irreversible cellular injury. "The highest resistin levels are found in patients with septic shock and AKI (90–120 ng/ml), raising the possibility that elimination of this cytokine depends on glomerular function." (PMID 28779451, 2017). "Plasma resistin levels are significantly higher in patients with septic shock and AKI when compared to patients with septic shock without AKI, and resistin also modulates the inflammatory response in those patients." (PMID 35062248, 2021).
systemic inflammatory response syndrome (4 papers, 2009 to 2021). SIRS is a serious condition related to systemic inflammation, organ dysfunction, and organ failure. "They emphasized that resistin concentration can be an early marker of systemic inflammatory response syndrome (SIRS), which can lead to the iatrogenic preterm delivery." (PMID 25548433, 2014).
uremia (4 papers, 2017 to 2024). A clinical syndrome associated with the retention of renal waste products or uremic toxins in the blood. "Leptin production is increased in adipocytes in uremic conditions and in mice, uremia increases resistin expression." (PMID 28333114, 2017). "It is possible that the rise in plasma resistin level reflects accumulation of that particular adipokine during reduced glomerular filtration rate (GFR), since plasma resistin concentrations have been found to be elevated in uremia." (PMID 30517161, 2018).
viral infections (4 papers, 2017 to 2025). "A possible role of resistin, along with other inflammatory mediators, is proposed in this pathology, which can be reduced by treating the viral infections, thereby breaking the vicious cycle of inflammation." (PMID 40724556, 2025). "This was supported by statistically significant findings showing higher levels of resistin in positive HSV seropositivity (p = 0.002) and HIV positivity (p = 0.018), suggesting that these viral infections can play a role in the modulation of resistin levels, a biomarker for proinflammation." (PMID 40724556, 2025). "There are a few studies investigating the significance of resistin in other acute virus infections." (PMID 30517161, 2018). "A high prevalence of viral infections (HSV and HIV) was observed with high resistin levels (>35 ng/mL), compared to low resistin levels." (PMID 40724556, 2025). "For both the SBI algorithm and the PERFORM algorithm, children with presumed bacterial infections had higher concentrations of PCT, NGAL and resistin than children with presumed viral infections or “non-SBI”." (PMID 34395340, 2021).